TLR4 (toll like receptor 4)
Diseases named in the same sentence as TLR4 in open-access papers (continued):
Sharing a sentence is not in itself a finding about the gene and the disease.
liver fibrosis (continued). "Its metabolites such as lipopolysaccharide (LPS) can conjugate with functional toll-like receptor 4 (TLR4) to activate reactive cells such as HSCs and Kupffer cells, and also enhance the activity of transforming growth factors thus leading to the development of liver fibrosis." (PMID 35222022, 2022). "Moreover, TLR4 expressed on Kupffer cells is involved in the fibrogenic signaling of HSCs and enhancing their response to transforming growth factor-1β (TGF-1β) thus promoting liver fibrosis." (PMID 34045968, 2021). "DOP reduced LPS entry into the liver to activate the TLR4/NF-κB signaling pathway, thereby reducing the production of inflammatory factors such as TGF-β and TNF-α, increasing the production of anti-inflammatory factors such as IL-10, and reducing the deposition of collagen to treat liver fibrosis." (PMID 32226380, 2020). "Therefore, although polarization to Th1 response was suggested to be involved with the increase of mortality of Schistosoma infection model, we observed alleviated liver fibrosis, without an increase of mortality in the TLR4-activated MSC group." (PMID 32503644, 2020). "Post-transcriptional suppression of TLR4 expression by let-7i has been shown to contribute to immune responses to C. parvum infection in cultured human cholangiocytes, and mu-miR-92a-2-5p, which targets TLR2, relieves Schistosoma japonicum-induced liver fibrosis." (PMID 32867835, 2020). "However, the direct relationship between palmitate and the TLR4 pathway in liver fibrosis has not been investigated." (PMID 30054551, 2018). "However, TLR4 signaling in Kupffer cells is not critical for the pathogenesis of experimental liver fibrosis." (PMID 22973518, 2012). "Furthermore long-term palmitate injection did not induce liver fibrosis in TLR4 KO mice." (PMID 30054551, 2018). "Common bile duct ligation (CBDL) and Carbon Tetrachloride-4 (CCl4)-induced liver fibrosis models were used in WT, IAP knockout (KO), and TLR4 KO mice supplemented with or without exogenous IAP in their drinking water." (PMID 33391458, 2021). "Results showed TLR4- and IFN-γ-activated MSC alleviated liver fibrosis in infected mice, without a significant increase of mortality, and unpretreated MSC showed no clear improvement; however, TLR2- and IFN-γ-activated MSC displayed aggravated immunopathology." (PMID 32503644, 2020). "However, the evidence to support this pathogenesis mechanism of LPS-activated TLR4 signaling comes largely from experimental NASH, data from carbon tetrachloride (CCl4)-induced liver fibrosis model has not been reported currently." (PMID 34603071, 2021). "However, the relationship among TLR4 signaling, TGM2, and liver fibrosis in HSCs has never been reported in the literatures." (PMID 29321784, 2017). "Furthermore, compared with the antifibrotic effects of PNS on DIO mice, PNS had less effective action on hepatic fibrosis in ob/ob mice, which might be due to the negative influence of PNS on CD14 and TLR4 activation." (PMID 33656663, 2021).
endotoxemia (235 papers, 2009 to 2026). "In mice subjected to a high-fat diet, quercetin restored gut microbiota balance and the associated endotoxemia triggered by Toll-like receptor 4 (TLR-4)-NF-κB signaling pathway activation." (PMID 38474354, 2024). "LPS-stimulated endotoxemia is mediated by Toll-like receptor-4 (TLR-4), which causes overwhelming production of tissue-damaging cytokines tumor necrosis factor-α (TNF-α), interleukin-1 (IL-1), and interleukin-6 (IL-6) and free radicals." (PMID 33875135, 2021). "It is already known that endotoxemia is associated with the occurrence of cirrhotic complications in patients with liver cirrhosis via activation of TLR4 signaling in KCs and HSCs." (PMID 34203178, 2021). "The occurrence of thrombotic complications was reduced in an endotoxemia model induced in TLR4-deficient mice." (PMID 34360659, 2021). "LPS induction causes endotoxemia, which is related to a significant increase in cardiac dysfunction, triggered via toll-like receptor 4 (TLR-4)-mediated inflammatory responses." (PMID 33573041, 2021). "The leachates then caused endotoxemia, leading to the upregulation of toll-like receptor 4 (TLR4) activation in the intestine as well as the brain." (PMID 30149548, 2018). "Resultant leaching of gut caused portal endotoxemia that led to upregulation of toll like receptor 4 (TLR4) activation in the small intestine and the brain." (PMID 28328972, 2017). "This NS5A-induced TLR4 is activated by endotoxemia associated with alcohol intake, leading to accentuated TLR4 signaling which in turn upregulates the stem cell marker Nanog required for TLR4-dependent liver oncogenesis." (PMID 21331379, 2010). "By reducing lipopolysaccharides (LPS) translocation from gram-negative bacteria into the systemic circulation, PUFAs lower endotoxemia and the subsequent activation of toll-like receptor 4 (TLR4)-mediated inflammatory pathways implicated in metabolic disturbances." (PMID 39796335, 2024). "When the gut barrier is impaired, intestinal Gram-negative bacteria release lipopolysaccharides (LPS) into the bloodstream, causing Toll-like receptor 4 (TLR4)-mediated endotoxemia, which induces pulmonary perivascular inflammatory responses and thus promotes the development of PAH." (PMID 36296961, 2022). "Thus, upregulation of TLR4 and its associated molecules by the Val variant is proposed here as the central mechanism for the enhanced response of Val carriers to endotoxemia observed in the in vivo LPS challenge previously." (PMID 36505401, 2022). "It was previously reported that mice fed a methionine choline-deficient diet demonstrated steatohepatitis, portal endotoxemia, and elevation of TLR4 expression in the liver, whereas TLR4 mutant mice showed less tissue damage and lipid accumulation in the liver." (PMID 34203178, 2021). "Utilising in vitro and in vivo approaches, we found evidence that supports our hypothesis and suggests that TLR4 inhibition warrants further investigation as a therapeutic strategy for endotoxemia-associated muscle weakness." (PMID 31959927, 2020). "Our finding that blockade of the TLR4–NF-κB signalling pathway reversed skeletal muscle loss suggests a potential new strategy for clinical intervention in skeletal muscle weakness induced by endotoxemia and subsequent systemic inflammation." (PMID 31959927, 2020). "TLR4 activation in response to fatty acids or LPS is implicated as yet another mechanism by which HF diet and dysbiosis induce impaired barrier function, low-grade inflammation and endotoxemia with detrimental effects on whole-body metabolism." (PMID 27125264, 2016). "Furthermore, hepatic encephalopathy is linked to endotoxemia and TLR4 single nucleotide polymorphism predicts the risk of liver cirrhosis in patients with chronic HCV." (PMID 25785448, 2015). "The endotoxemia that occurs after strenuous exercise results in increased circulating LPS and may be another mechanism underlying the elevation in TLR-4 and NF-kBp65 protein expression." (PMID 20920329, 2010).
endotoxemia (continued). "In contrast, dietary patterns characterized by high saturated fat and refined carbohydrate intake—negatively weighted within the DI-GM—have been associated with gut dysbiosis and elevated endotoxemia, which may exacerbate periodontal inflammation via TLR4/MyD88 pathways." (PMID 40880748, 2025). "Acute endotoxemia caused a long-lasting increase in mRNA expression of inflammatory markers such as TLR-4, CD14 and serum amyloid A (SAA) in the adipose tissue, which may represent the key factors connecting inflammation to increased susceptibility to weight gain and impaired glucose homeostasis." (PMID 35335996, 2022). "Thus, TLR4-mediated muscle catabolism may take occur in many conditions associated with cachexia in addition to endotoxemia." (PMID 31959927, 2020). "Among FMT recipients, the reduced expressions of Tlr4 and Nod2 compared to H reflected lower inflammation, implying that their improved metabolism might associate with the mitigated endotoxemia by receiving FMT from exercised donors." (PMID 30353027, 2018). "In future investigations os the effects of coacervate whey protein we suggest the evaluation of antioxidant enzymes activity, which may additionally illustrate the inflammatory cascade of TLR-4 activated by LPS, reflecting the endotoxemia caused by high-fat diet administration." (PMID 24673809, 2014). "We report here that a filarial glycoprotein binds to murine macrophages and human monocytes through TLR4 and activates them through alternate pathway and in the process inhibits LPS mediated classical activation which leads to inflammation associated with endotoxemia." (PMID 22654663, 2012). "The contribution of TLR4 activation to myocardial AEA formation in the context of binge alcohol-induced endotoxemia using Tlr4–/– mice was also investigated." (PMID 41205808, 2026). "This dual protection aligns with reports that DIO suppresses the TLR4-MyD88-NF-κB axis, thereby reducing endotoxemia and interrupting the vicious cycle of gut-derived inflammation and renal injury." (PMID 40458807, 2025). "Green tea extract restores liver metabolism, likely through its anti-inflammatory effects mediated by the endotoxemia/TLR4/NF-κB pathway." (PMID 39067063, 2025). "These approaches improve intestinal barrier integrity, reduce endotoxemia, and inhibit hepatic inflammatory pathways (via TLR4/NF-κB), thereby attenuating disease progression." (PMID 40647333, 2025). "To answer these foundational questions, we established a reductionist model that mimics IFN-I levels (recombinant IFN-β; a representative of IFN-Is) and/or increased endotoxemia (purified, TLR4 specific, LPS; mimic of endotoxemia) in an obese microenvironment." (PMID 41277555, 2025). "Patients with MASLD often exhibit increased intestinal permeability, endotoxemia, and Toll-like receptor 4 (TLR4) activation." (PMID 41438070, 2025). "As clinical manifestations of endotoxemia are largely due to LPS/TLR4 signaling, the administration of LPS in rodents provides a highly reproducible experimental model for studying endotoxemia, septic shock, and hepatic inflammation." (PMID 40283890, 2025). "Rifaximin, a gut-selective antibiotic, modulates intestinal microbiota composition, reduces endotoxemia, and downregulates toll-like Receptor 4 (TLR4)-mediated liver inflammation." (PMID 41199753, 2025). "It improved AOM/DSS-induced microbial dysbiosis, increased the production of short-chain fatty acids, alleviated endotoxemia, and improved intestinal shielding function by inhibiting TLR4/MyD88/NF-κB signaling." (PMID 40507156, 2025). "Binding of LPS with LBP is the first step in activating the CD14:TLR4 pathogen recognition pathway, and even subclinical amounts of LPS in circulation are considered evidence of systemic endotoxemia." (PMID 40427905, 2025). "This aligns with prior work indicating that gut permeability and endotoxemia can activate TLR4 and initiate downstream inflammatory signaling during heat stress." (PMID 40507928, 2025).
endotoxemia (continued). "During endotoxemia, immune cells recognize LPS through the Toll-like receptor 4 (TLR4)/MD2 complex, resulting in the activation of the NF-κB signaling pathway and the production of proinflammatory cytokines and free radicals, such as ROS and RNS." (PMID 41169942, 2025). "In humans subjected to experimental endotoxemia, a 2- to 3-fold increase in CD 11b, TLR4, and TLR2 expression is observed in circulating blood monocytes, implicating the involvement of PU.1 in inflammatory signaling." (PMID 38662666, 2024). "Next, we validated the improvement of disease severity by Cmtm3 knockout through the TLR4 pathway in an LPS-induced endotoxemia model." (PMID 39455728, 2024). "Specifically, hyper-endotoxemia interacts with toll-like receptor 4 (TLR4) in Kupffer cells and produces NADPH-oxidase (NOX)-dependent ROS and HSCs." (PMID 39594528, 2024). "The results showed that Cmtm3 KO reduced the pathological injury in the liver, lungs, and kidneys of LPS-induced endotoxemia mice, while TLR4 overexpression reversed this alleviating effect." (PMID 39455728, 2024). "The likely-resulting endotoxemia from intestinal barrier dysfunction stimulates toll-like receptor 4 (TLR4) in Kupffer cells to produce NADPH-oxidase (NOX)-dependent ROS and activate HSCs, leading to fibrosis." (PMID 38214802, 2024). "For example, lipopolysaccharide (LPS), a key mediator of endotoxemia, can activate an inflammatory response through the toll-like receptor 4/myeloid differentiation factor 88 (TLR4/MyD88) signaling pathway." (PMID 38472186, 2024). "The development of bacterial translocation and endotoxemia from an impaired intestinal barrier lead to hepatic inflammation and injury, likely through the activation of toll-like receptor-4 (TLR4)." (PMID 39200311, 2024). "Survival analysis indicated that Cmtm3 KO significantly improved the survival rate of LPS-induced endotoxemia mice, while TLR4 overexpression increased the mortality rate of Cmtm3 KO mice." (PMID 39455728, 2024). "Cmtm3 KO alleviated the release of TNF-α, IL-1β, and IL-10 in the peripheral blood of LPS-induced endotoxemia mice, while TLR4 overexpression reversed this alleviating effect." (PMID 39455728, 2024). "Improved gut barrier integrity, reduced endotoxemia, decreased TLR4 signal and inflammation; reduced the number of macrophages." (PMID 36671814, 2023). "The presence of high levels of blood lipopolysaccharides (LPSs), a condition known as endotoxemia, leads to the activation of the hepatic Toll-like receptor 4 (TLR4)/myeloid differentiation factor 88 (Myd88) pathway after long-term alcohol consumption." (PMID 37240190, 2023). "Previous studies have identified the expression of both TLR-4 and RAGE in cardiomyocytes, and genetic deficiency of TLR-4 in cardiomyocytes is known to protect against cardiac dysfunction in endotoxemia." (PMID 37773186, 2023). "Endotoxemia potentiates the TLR4/MyD88/NF-κB signaling in macrophages to secrete TNF and enhances fatty acid accumulation upregulating the expression of ACC1 (Acaca) and FAS (Fasn)." (PMID 37345131, 2023). "Ameliorated microbiota dysbiosis, increased the production of short-chain fatty acids, and alleviated endotoxemia by inhibiting the TLR4/MyD88/NF-κB signaling pathway." (PMID 37485384, 2023). "Alcohol consumption causes liver infiltration by neutrophils and disintegration of the intestinal barrier, leading to endotoxemia, which triggers the secretion of NETs by hepatic neutrophils, stimulating the TLR4 pathway to promote steatohepatitis." (PMID 37345131, 2023). "Diet-induced obesity (DIO) is associated with a leaky gut in both animals and humans, which increases chronic bacteremia and endotoxemia capable of initiating systemic inflammation and insulin resistance via the activation of the TLR4-NF-κB pathway." (PMID 37181127, 2023). "As LPS triggers the activation of the Toll-like receptor-4 (TLR-4) inflammatory pathway, PACs can minimize endotoxemia." (PMID 36670878, 2022).
endotoxemia (continued). "We found that deletion of TLR4 from myofibers resulted in few changes in systemic cytokine concentrations during early endotoxemia." (PMID 35814217, 2022). "Our previous study showed that cell surface expression of the TLR4 is increased in BMDMs during LPS-induced endotoxemia." (PMID 36344490, 2022). "This endotoxemia creates an inflammatory environment by producing pro-inflammatory cytokines, hepatic toll-like receptor 4 (TLR4), and plasma plasminogen activator inhibitor 1 expression that develops IR and hepatic lipid build-up." (PMID 36320966, 2022). "This causes intestinal infection and endotoxemia, and endotoxin activates transcription factors NF-κB and AP1 through Toll-like receptor 4 (TLR4) and promotes inflammatory cytokines such as TNF-α, IL-1, IL-6, and MCP-1." (PMID 36160423, 2022). "The mechanisms of QRQZ on NASH were associated with modulating gut microbiota, thereby inducing the tight junction of gut barrier, reducing the endotoxemia and inhibiting the activation of TLR4/NF-κB signaling pathway in liver." (PMID 36743916, 2022). "The mechanisms of QRQZ on NASH were associated with modulating gut microbiota, thereby inducing the tight junction of gut barrier, reducing the endotoxemia and inhibiting the activation of TLR4/NFkB signaling pathway in liver." (PMID 36743916, 2022). "We further found that LPS induced the increase of cell surface TLR4 expression responsible for the production of ROS and subsequent parthanatos in endotoxemia." (PMID 34282120, 2021). "Endothelial TLR4 is the primary intravascular guarding system to detect bacterial invasion, and endothelial TLR4 is responsible for the recruitment of neutrophils to peripheral tissues in systemic endotoxemia." (PMID 33839697, 2021). "Increased gut permeability, in turn, further exacerbates chronic inflammation via endotoxemia and TLR4 pathway activation, leading to neuroinflammation and oxidative/nitrosative stress." (PMID 34768601, 2021). "In conclusion, we have found that the occurrence of parthanatos in endotoxemia and erlotinib can significantly mitigate LPS-induced parthanatos in vivo and in vitro via suppressing cell surface TLR4 expression." (PMID 34282120, 2021). "Recent studies have shown increased gut permeability with subsequent low-grade endotoxemia, enhanced artery thrombosis and platelet activation in a TLR4-dependent manner in patients with ST-elevation myocardial infarction (STEMI)." (PMID 34944024, 2021). "During endotoxemia, LPS that are present in the blood can be recognized by the innate immune cells, mostly via the toll-like receptor-4 (TLR-4) which initiates the inflammatory cascade." (PMID 34712716, 2021). "Local cytokine production is coordinated in response to LPS assault, resulting in downstream TLR4 signaling activation and LPS-mediated endotoxemia." (PMID 34830401, 2021). "Our findings are the first to demonstrate that Fen possesses anti-ALD properties, potentially through modulation of the intestinal barrier function, endotoxemia, and TLR4-mediated inflammation." (PMID 33815111, 2021). "The biological plausibility of this finding relies on previous experimental study showing that low-grade endotoxemia amplifies thrombus growth through interaction with its receptor TLR4 at level of platelets or leucocytes." (PMID 34092777, 2021). "Low-grade endotoxemia in SIBO will activate the TLR-4 and CD14 receptors, which will activate the NF-κB pathway and lead to the expression of inflammatory cytokines." (PMID 34855819, 2021). "In chronic alcohol exposure and endotoxemia, LPS promotes an inflammatory response through TLR4, which in the liver is expressed in both hepatocytes and Kupffer cells." (PMID 33815111, 2021). "Endotoxemia and TLR4 signaling control the production of proinflammatory cytokines in target tissues and lead to chronic inflammation and insulin resistance in fat mice." (PMID 32685087, 2020).